AR (androgen receptor)
Diseases named in the same sentence as AR in open-access papers (continued):
Sharing a sentence is not in itself a finding about the gene and the disease.
tumor (continued). "Collectively these studies have shown that while ADT decreases serum testosterone levels by approximately 95%, intra-tumor androgen levels combined with overexpressed AR may be sufficient to drive the progression of PCa in AR-dependent manner." (PMID 22746994, 2012). "Finally, testosterone and dihydrotestosterone probably up-regulate intratumor AR synthesis, which would account for the frequent co-existance of ER and AR in the same tumor." (PMID 23241075, 2012). "Men with CPRC often exhibit an increase in tumor androgen receptor (AR) levels." (PMID 22509301, 2012). "AR induction of cellular senescence may be interpreted as a tumor suppressive action, or as inappropriate oncogene activation, similar to Ras and Myc." (PMID 22403609, 2012). "No functional AR mutations were found in the PAC120 tumor but appeared in 28% (10/36) of AI variant tumors." (PMID 22879924, 2012). "Tumors with high AR expression were less frequently associated (not significantly) to the large tumor size — ≥2 cm — than tumors with AR-absent expression (29% vs. 45%)." (PMID 23241075, 2012). "Moreover, the evidence of AR anti-proliferative and anti-tumor effects in the prostate emerges continuously." (PMID 22403609, 2012). "To determine whether let-7c exhibits anti-proliferative effects on PCa xenografts in vivo, we injected 2x106 C4-2B or PC346C (both cell lines are AR-positive) cells s.c. into both flanks of male nude mice and monitored tumor development." (PMID 22479342, 2012). "This clearly demonstrates that clonal evolution occurs over time in response to therapy and that tumor cells with different patterns of somatic alterations in the AR pathway may display variable responses to different modes of ADT." (PMID 22956944, 2012). "Elevated androgen receptor (AR) activity and enhanced survival in the cancer cells may be contributing factors, but stromal cells in the tumor microenvironment also play an important role." (PMID 22880071, 2012). "It has been proposed that IL-6 may support androgen-independent tumor growth by enhancing androgen receptor (AR) expression/activity." (PMID 22046506, 2012). "This may seem unusual, considering that it was already well known that the majority of PCa cases are androgen dependent for tumor growth and indeed express AR, and drugs were already being manufactured to ablate AR activity." (PMID 22111002, 2011). "This may also explain the correlation that exists between levels of MAPK in the nucleus and levels of AR found in CRPC tumours." (PMID 21559022, 2011). "MDV3100 is an AR antagonist that blocks androgen binding and prevents nuclear translocation and recruitment of coactivators; it has been shown to confer a tumor response in men with CRPC after failure of prior hormonal therapy, with 43% showing a ≥50% PSA response in a phase 1/2 study." (PMID 21513551, 2011). "In prostate carcinoma cells, an increase in RIIbeta expression inhibits tumor growth, while an increase in RIalpha stimulates tumor growth; in these tumors, the cAMP pathway may also interact with the androgen receptor, by enhancing its activation." (PMID 24212646, 2011). "All male mice displayed hyperproliferation, neoplasias, and eventually microinvasive HGPIN, indicating that AR is a positive regulator of cellular proliferation and that mouse prostates are more susceptible to PCa upon AR overexpression." (PMID 22111002, 2011). "However, clinical studies showed that the AR is rarely lost but is often increased in CRPC tumor specimens and their metastases." (PMID 21980429, 2011). "An another approach very similar to that described in the present report was used to map nuclear receptor-dependant tumor translocations by the androgen receptor, although important technical considerations reported in the present paper to improve efficiency were not provided." (PMID 21364894, 2011).
tumor (continued). "We identified that panobinostat/everolimus combination resulted in enhanced anti-tumor activity mediated by decreased tumor growth concurrent with augmentation of p21 and p27 expression and the attenuation of angiogenesis and tumor proliferation via androgen receptor, c-Myc and HIF-1α signaling." (PMID 22087262, 2011). "By combining everolimus with panobinostat we elude possible tumor escape mechanisms in response to mTOR inhibition (increased AR transcriptional activity and expression of known onco-miRs), resulting in, at least with this combination, cytostatic anti-tumor activity." (PMID 22087262, 2011). "Additionally, to determine if AR status promoted the rate of tumor growth, we divided the CRPC bone metastasis samples into three groups: N+C+ (n = 93), N+C↓ (n = 39), and N-C- (n = 18)." (PMID 22114732, 2011). "The three AR diplotypes in group B were associated with shorter disease-free survival compared with the AR diplotypes in group A. Patients in group B also presented with higher BMI, larger total breast volume, larger tumours, and a higher frequency of axillary lymph node involvement." (PMID 22033271, 2011). "Conversely, increased androgens and AR expression following AI treatment may contribute to reduced tumour cell proliferation." (PMID 22033271, 2011). "Although the inhibition of AR and signal transduction proteins with bicalutamide plus everolimus is effective, treatment with VN/124-1 in combination with everolimus was superior in maintaining tumour growth suppression in the HP-LNCaP xenograft." (PMID 20842117, 2010). "Furthermore, AR signalling seems to play a growth suppressing function in the initial stage of tumour development." (PMID 20663219, 2010). "This is consistent with the AR still being present in the HP-LNCaP-resistant tumours." (PMID 20842117, 2010). "This tumor may be an example of the recently described apocrine-like carcinoma which includes AR and ER positive tumors." (PMID 20712882, 2010). "While the current androgen deprivation therapy represses the expression of growth promoting genes that are activated by the AR, it may also attenuate the suppressive role of AR on c-Met expression and contribute to tumor progression." (PMID 20946682, 2010). "Improved understanding of the interaction between the AR and alternate signalling pathways could yield a better strategy for treating tumour progression that may delay, re-sensitise, or prevent CRPC." (PMID 20842117, 2010). "Furthermore, five of the top ten NR genes that were shown to differ significantly between tumor and normal tissue were common to both datasets (i.e., AR, MR, NGFIB3, PPARγ, and RXRγ)." (PMID 21179495, 2010). "Our finding of no alteration of androgen receptor expression with methylselenocysteine consumption differs from consumption and intraperitoneal injection of methylselenocysteine that decreased androgen receptor expression in the rat prostate and LNCaP tumor xenographs in nude mice, respectively." (PMID 20454690, 2010). "Thus, we measured androgen receptor and probasin mRNA expression in the normal prostate and tumor of all dietary groups." (PMID 20454690, 2010). "In the present study, we explored whether cystatin C is related to AR in androgen-independent tumor cell invasion and metastasis." (PMID 19956729, 2009). "We therefore hypothesised that the presence of a TMPRSS2–ERG fusion gene could indicate dependance on AR signalling and consequently define a tumour sub-group that is responsive to abiraterone acetate." (PMID 19223900, 2009). "Mechanisms such as AR amplification (resulting in increased sensitivity to androgens) do occur, but the resultant tumour may well arise from a more primitive AR− clone." (PMID 19040209, 2009). "The AR can act either as a promoter or a tumor suppressor depending on cell types." (PMID 19668381, 2009).
tumor (continued). "This response is short lived and tumour cells may re-emerge independently of androgen stimulation by acting through several mechanisms, including amplification of the AR gene or bypassing the AR by deregulating apoptotic genes." (PMID 19844236, 2009). "The observation that androgen deprivation results in increase in AR expression highlights the importance of AR in this stage of disease and suggests that other ligands may be capable of binding and activating AR to drive tumour cell growth." (PMID 19337256, 2009). "Cystatin C is associated with the proteolytic cascade and MAPK/Erk pathway together with AR may act in a synchronized manner to promote tumor growth and invasion into surrounding tissues." (PMID 19956729, 2009). "That hypothesis is based on the observation that most hormone-refractory tumours continue to express AR and androgen-regulated genes, such as PSA6." (PMID 19040209, 2009). "However, the same study also showed that the AR levels decreased with increasing tumor grade in BC, which has been corroborated by steroid binding and immunohistochemical studies." (PMID 18433501, 2008). "When expression levels in hormone-sensitive or -refractory tumours were used to investigate a link between activation of the PI3K pathway and development of hormone-refractory disease, only AR phosphorylated at the Akt consensus site was associated with survival." (PMID 18349820, 2008). "This suggests that the AR in normal adjacent tissues may play a different role as compared to the AR in tumor tissue where the high AR expression appears to be implicated in progression to hormonorefractory disease." (PMID 19025630, 2008). "In addition, expression levels of pAR210 and AR strongly correlate with pAkt473 expression levels only in the refractory tumours, suggesting that it is only when androgen levels are low that this pathway is activated." (PMID 18349820, 2008). "Similarly, treatment of mice bearing 22RV1 tumors (mean tumor volume on the day of first siRNA administration: 224.6±104.0 mm3) with AR-siRNA markedly repressed the tumor growth." (PMID 17925854, 2007). "Moreover, therapeutic efficacy is clinically monitored by reductions in serum PSA (prostate specific antigen), as expression of PSA is dependent on AR activity in prostatic cells and correlates with tumour burden." (PMID 17375037, 2007). "AR-siRNA induced in all three tumor models a strong inhibitory effect." (PMID 17925854, 2007). "By targeting multiple pathways, including AR signaling, it is feasible that it may possible to treat patients with tumor-specific ‘tailor-made’ therapies in the future." (PMID 19675761, 2007). "The AR is expressed in the normal breast, as well as in primary and metastatic breast cancer tumours, and both the expression and protein levels are correlated with tumour invasiveness." (PMID 16987421, 2006). "The greater AR heterogeneity in poor responders may reflect a greater genetic instability in tumours that have progressed toward androgen independence i.e., many of the growth factors may exhibit their effects via crosstalk with AR." (PMID 16759347, 2006). "Moreover, deregulation of AR activity has been validated in tumor models to be sufficient for therapeutic bypass." (PMID 16863592, 2006). "However, an increase in AR expression was seen with the development of AR amplification in paired tumours." (PMID 12888829, 2003). "Moreover, GSEA results demonstrated significant enrichments of prognostic immune signatures in tumor samples after AR signaling inhibition by enza treatment, including the Hallmark IFNγ signaling signature, the 18-gene T cell–inflamed GEP, and ICR 20-gene signatures." (PMID 41486951, 2026). "Notably, patients with concurrent high expression of YAP and AR exhibited the shortest PFS among all groups, suggesting that YAP and AR may accelerate tumor progression through a synergistic mechanism." (PMID 41517748, 2026).
tumor (continued). "This study identifies a unique AR-positive tumor-associated macrophages (AR+ TAMs) subpopulation, enriched in ENZ-resistant patients and correlated with poor prognosis, which acquires functional AR protein not through endogenous expression but via ANXA2-dependent phagocytosis of tumor cells." (PMID 41990247, 2026). "However, its role in promoting tumor cell proliferation is dependent on AR signaling." (PMID 41431399, 2026). "However, in another recent study using TUR (n = 143) and radical cystectomy (n = 198) specimens, there were no strong correlations between AR expression in tumor cells and PD-L1 expression in tumor cells or tumor-associated immune cells." (PMID 40486871, 2025). "It was suggested that AR could have a tumor suppressor role at least in one subtype of RCC." (PMID 41034844, 2025). "NRs such as androgen receptor (AR), estrogen receptors (ERα and ERβ), peroxisome proliferator-activated receptors (PPARs), and glucocorticoid receptor (GCR) are implicated in BCa pathogenesis through their modulation of oncogenic and tumor suppressive pathways." (PMID 40806474, 2025). "Additionally, the different hormonal environments in humans and dogs, including the effects of estrous cycles in canines, may also modulate AR expression and its impact on tumor biology." (PMID 40286049, 2025). "Similarly, AR inhibition may alter the tumor immune milieu by shifting the balance between immune-supportive and immune-suppressive cell populations, thereby augmenting the effectiveness of checkpoint blockade." (PMID 41373752, 2025). "Moreover, we performed RTqPCR on the AR mRNA in the tumor lysates of the PEG-DSG-LNPs treated animals to see whether we could measure enhanced knockdown in the liposome group compared to the control group 24 h after treatment." (PMID 40115963, 2025). "Similarly, pre-clinical evidence indicates inhibition of tumor growth by an AR degrader bavdegalutamide (ARV-110, a proteolysis targeting chimera, PROTAC) that especially in combination with abiraterone showed potent inhibition of growth in patient-derived xenograft and mouse model." (PMID 41264145, 2025). "In this setting, AR gene amplification and overexpression enable tumors to respond to even minimal levels of androgens or weak agonists, while mutations in the receptor’s LBD, such as T877A or F876L, can convert certain anti-androgen factors into partial agonists that promote tumor growth." (PMID 40427518, 2025). "In prostate cancer fibroblast and tumor microenvironment models, AR activation has been linked to upregulation of MMP-9/VEGF signaling via PIP5K1α/AKT crosstalk, implicating a molecular axis by which androgen signaling promotes proteolysis and vascular remodeling in tumor stroma." (PMID 41304763, 2025). "These factors could promote tumor proliferation and survival independently of the AR pathway." (PMID 41079787, 2025). "Thus, AR may exert either tumor-promoting or tumor-suppressive effects depending on the molecular and clinical context, highlighting the need for further mechanistic studies." (PMID 40940929, 2025). "While our data do not allow to draw causal conclusions in terms of the interplay between CAFs and AR expression in tumor cells, SDC patients with ARhigh tumors could particularly benefit from CAF-targeted therapies or therapies combining androgen blockade and CAF-targeting." (PMID 41083996, 2025). "Whether chemotherapy influences the association of steroid levels with response to AR axis therapy is not well understood, nor whether steroid levels influence the association of tumor volume with response to chemotherapy." (PMID 39588946, 2025). "Interestingly, a recent study collecting circulating tumor cells from patients treated with AR signaling inhibitors demonstrated that detection of multiple NE markers — independent of the loss of AR target gene expression — was sufficient for the detection of NEPC." (PMID 41023204, 2025).
tumor (continued). "In vitro experiments using androgen-responsive LNCaP prostate adenocarcinoma cells have demonstrated that phages modulate the expression of genes involved in cell proliferation, viability, and androgen receptor signaling, suggesting that they may serve as modulators of tumor biology in PCa." (PMID 41384118, 2025). "Furthermore, the CYP3A4*1B promoter variant is linked to higher tumor grade and advanced tumor stage due to ineffective androgen deactivation rather than direct regulation of AR expression." (PMID 41514571, 2025). "The increased abundance of HER2 activity in enzalutamide-resistant PCa cells raises the possibility that treatment with inhibitors against HER2 (or other RTK) may either increase tumor cell AR activity or enrich for the population of tumor cells that is harboring greater AR activity." (PMID 40906535, 2025). "However, blocking tumor AR activity is a standard therapeutic method." (PMID 41228208, 2025). "This relative preservation of pathway integrity may indicate that OMPC tumours rely more on AR signalling than on alternative oncogenic pathways for survival, making them more susceptible to AR-targeted therapies and potentially less prone to early treatment resistance." (PMID 40282432, 2025). "Notably, elevated expression of specific genes in CAFs may suppress AR signaling in tumor cells and exacerbate castration resistance." (PMID 40607407, 2025). "Thus, AR inhibition may reduce tumor OXPHOS and activate lipotoxicity of ER+ BC metastases to liver and lung." (PMID 41216931, 2025). "Observations indicate that the expression levels of tumor stemness markers tend to rise with tumor progression, and it has been shown that PCa neuroendocrine cells (AR and PSA negative) may be associated with CSCs." (PMID 40519259, 2025). "Indeed, AR signaling in the stroma has been reported to play a protective role in PCa development, as low AR expression in the TME is associated with a high-grade tumor and poor clinical outcome." (PMID 38383542, 2024). "Reduce AR-driven tumor growth, though resistance may occur in high AR activity cases." (PMID 39600743, 2024). "Our work thus illuminates a profound dysregulation of this cell cycle-regulated network and facilitates a deeper understanding of the tumor biology of AR-low TNBC and potentially QNBC while also pointing to possible treatment targets that might specifically benefit this high-need patient subgroup." (PMID 39335162, 2024). "In addition, inhibition of AR‐independent signalling pathways (like Akt/mTOR pathway) by nodularin‐R may enhance the combined anti‐tumour effects." (PMID 39550701, 2024). "However, generally accepted therapies for high-grade SGC may include cytotoxic chemotherapy and therapies targeting tumour molecular alterations like androgen-receptor blockers and HER2-directed therapies." (PMID 39330047, 2024). "Interestingly, the AR has both oncogenic and tumor suppressive functions." (PMID 39668349, 2024). "In addition, several studies have postulated that AR expression could favor tumor progression in TNBC." (PMID 38338747, 2024). "Thus, targeting the Gln metabolic network as an Achilles’ heel of PCa offers unique opportunities to tackle therapy resistance and sensitize tumor cells to anticancer treatments and might be more advantageous than targeting AR alone." (PMID 39199642, 2024). "Therefore, sTK1 levels could reflect tumor aggressiveness and could thus predict the response to androgen receptor–targeted therapies." (PMID 39525979, 2024). "Therefore, targeting both tumor epithelial AR and stromal AR signaling could simultaneously disrupt the tumor microenvironment and inhibit epithelial tumor growth." (PMID 39369165, 2024). "Interestingly, the AR has both tumor suppressive and oncogenic function." (PMID 39668349, 2024).